IL33 (interleukin 33)
Diseases named in the same sentence as IL33 in open-access papers (continued):
Sharing a sentence is not in itself a finding about the gene and the disease.
inflammation (continued). "We demonstrated that clodronate treatment inhibited airway inflammation and IL-33 release, which indicated that inflammatory monocytes recruited to the lung had a crucial role in HDM-induced airway inflammation." (PMID 27310495, 2016). "These animals develop spontaneous joint inflammation and cartilage destruction, but the administration of IL-33 inhibits the TNF-α-induced bone destruction via the IL-33/ST2 axis." (PMID 24692848, 2014). "IL‐33 activated the expression of PI3K/AKT proteins, which are involved in the activation of ILC2s that might be important in aggravating eosinophilic inflammation in patients with EA." (PMID 37357549, 2023). "IL-33 is considered to be a driving factor of early inflammation, so some scholars used IL1-RL1 (sST2) to treat OVA-induced airway inflammation in mice, and found that IL1-RL1 can reduce airway inflammation." (PMID 35578178, 2022). "Using a murine model exhibiting persistent airway inflammation we sought to understand the effect of PI3Kδ inhibition, montelukast and anti-IL5 antibody treatment on IL33 expression, group-2-innate lymphoid cells, inflammatory eosinophils, and goblet cell metaplasia." (PMID 34920698, 2021). "Our results indicate that IL-33 is involved in the development of eosinophilic airway inflammation in non-atopic COPD patients." (PMID 29859068, 2018). "Reduced inflammation would result in diminished killing of bacteria, which would be in line with evidence that in ovalbumin-induced airway inflammation IL-33 does not affect NO production from iNOS." (PMID 29867945, 2018). "However, the role of IL-33 and IL-33/ST2 signaling in establishment of pulmonary inflammation and fibrosis is not well understood." (PMID 29988569, 2018). "These animals developed spontaneous joint inflammation and cartilage destruction and the administration of IL-33 inhibited the TNF-α-induced bone destruction via the IL-33/ST2 axis, which was confirmed using an ST2 agonist antibody that triggered the same downstream regulators." (PMID 24692848, 2014). "This epithelial injury triggers the release of alarmins IL-33 and TSLP, activates innate lymphoid cell types 2 (ILC2) and T cells, and promotes IL-5/IL-13-driven eosinophilic and interleukin-17A-mediated neutrophilic inflammation—resulting in mixed airway inflammation." (PMID 41450494, 2025). "IL-33 signaling is involved in both allergic and non-allergic eosinophilic inflammation." (PMID 35720347, 2022). "Herein, we hypothesize that in addition to mediate allergic airway inflammation and remodeling, epithelium‐derived triple cytokines, IL‐25/IL‐33/TSLP, can also potentiate non‐atopic lung parenchymal inflammation and fibrogenesis mainly by initiating and propagating type 2 immunity." (PMID 36082495, 2022). "Our results showed that Renifolin F could downregulate the expression of microRNA-155, possibly by reducing the production of IL-33 to inhibit the activation of the IL-33/ST2 axis, thereby, reducing the production of ILC2s to prevent the occurrence of airway inflammation." (PMID 35744915, 2022). "Importantly, both IL-33 and IL-25 could activate ILC2, leading to production of IL-5 and IL-13, which mediates lung inflammation." (PMID 34970267, 2021). "As exogenous IL-33 does not induce jejunal inflammation in the same mice in which it induces pancreatic inflammation, we have discovered a potential role for an IL-33/acinar cell axis in the recruitment of neutrophils and macrophages and the exacerbation of acute pancreatic inflammation." (PMID 23418608, 2013). "Similarly, airway exposure to the common fungal aeroallergen Alternaria alternata upregulates IL-33, IL-5, and IL-13 levels in the bronchoalveolar lavage of mice and induces eosinophilic airway inflammation, however, this inflammation does not develop when the mice lack IL-33 or ILC2s." (PMID 36466877, 2022).
inflammation (continued). "Besides, the correlations between BIRC3 expression and asthmatic eosinophilic/allergic inflammation indicators (FeNO, IgE, and EOS%), pulmonary function (FEV1, FEV1% pred, FVC% pred, and FEV1/FVC), and inflammatory cytokines (IL-4, IL-5, IL-13, IL-25, IL-10, IL-33, and TSLP) were analyzed." (PMID 35287655, 2022). "As a growing body of evidence confirms the importance of IL-33-induced ILCs in the protection against parasites, to date, the potential role of these novel cells in spontaneous inflammatory conditions has not been fully characterized in models of intestinal inflammation." (PMID 23766561, 2013). "Although IL-33 and mast cell interactions may contribute to disease pathogenesis, our findings suggest that IL-33 and acinar cell interactions may have a distinctive role in the early phase of the development of acute pancreatic inflammation that is independent of mast cell degranulation." (PMID 23418608, 2013). "On the other hand, only IL-33, but not IL-25 or TSLP, was important for induction of HDM-induced airway inflammation in mice sensitized “intranasally” with HDM35,36." (PMID 30082755, 2018). "On the other hand, it was reported that the phenotypes of ST2-/- mice did not completely correspond with those of IL-33-/- mice in certain disease models, such as OVA-induced airway inflammation and collagen-induced arthritis." (PMID 26230091, 2015). "On the other hand, IL-33, but not IL-25 or TSLP, was found to be important for development of HDM-induced “chronic” airway inflammation in mice." (PMID 24205109, 2013). "However, IL-33, but not IL-25 or TSLP, was shown to be responsible for development of airway inflammation in mice sensitized “intranasally” with house dust mite antigens." (PMID 26230091, 2015).
cardiovascular diseases (65 papers, 2008 to 2025). "Studies in animal models suggest that IL-33/ST2 is implicated in cardiovascular disease and signaling as an important protective pathway in various heart diseases including HF." (PMID 24385685, 2013). "Therefore, our results demonstrated that IL-33 is closely related to risk factors of cardiovascular disease (e.g. blood pressure, blood lipid level)." (PMID 33541367, 2021). "This review discusses the current understanding of the role of these recently identified interleukins, such as IL-27, IL-31, IL-32, IL-33, and the IL-28 group (IL-28A, IL-28B, IL-29), in the development of cardiovascular diseases." (PMID 39844544, 2025). "Studies have revealed that sST2 attenuates the biological effects of IL-33 and aggravates various cardiovascular diseases when exploring potential novel therapeutic targets for cardiovascular diseases." (PMID 39596071, 2024). "The ST2/IL-33 represents one of the most complex pathways as it is involved in different pathophysiological conditions, and also in cardiovascular diseases." (PMID 37371771, 2023). "In cardiovascular disease, IL-33 secretion is considered to be protective since it reduces atherosclerotic plaque progression." (PMID 36768322, 2023). "A systematic review of the association between the IL-33/ST2 axis and CAD revealed that IL-33/ST2 plays a protective role in CAD and serum sST2 and IL-33 levels are increased in patients with cardiovascular disease." (PMID 36337880, 2022). "IL-33 plays a role in cardiovascular disease either at the genetic level through regulation of transcription or as a classically active IL-33 functions that acts as an “alarmin” or cytokine." (PMID 36337880, 2022). "The mechanism of IL-33 in cardiovascular disease acts on the one hand at the genetic level through regulation of transcription, and also through a classically active IL-33 as an “alarmin” or cytokine." (PMID 36337880, 2022). "Various studies reported that the effect of IL-33 in cardiac patients became worse, as an increasing level of this cytokine prognosticates cardiovascular disease events." (PMID 34754275, 2021). "In the past, we have investigated the sST2/IL-33 axis in different cardiovascular diseases and gained good experience with sST2 as a powerful indicator of generalized inflammation as well as a prognostic parameter." (PMID 34741120, 2021). "11In cardiovascular disease models, IL-33 induction following vascular and cardiac stress was correlated with improved outcomes." (PMID 32286393, 2020). "Using our search criteria, only three studies focused exclusively on mice, and these studies focused on regulatory roles for IL-33 in cardiovascular disease." (PMID 32486265, 2020). "In cardiovascular disease models, IL-33 was demonstrated to promote tissue repair and protect against inflammation via expansion of Treg and ILC2." (PMID 33182616, 2020). "Recent studies have demonstrated that interleukin-33/suppression of tumorigenicity 2 (IL-33/ST2) signaling plays a critical role in the pathogenesis of several cardiovascular diseases." (PMID 31235844, 2019). "The plasma concentration of suppression of tumorogenicity (sST2), a surrogate marker of IL-33 production, is a prognostic marker of cardiovascular disease." (PMID 28553430, 2017). "Studies have been conducted in recent years and have reported that IL-33/ST2 has an active role in cardiovascular diseases." (PMID 28614418, 2017). "Several studies have been conducted on animals, and the reports show that IL-33/ST2 has an active role in cardiovascular diseases." (PMID 28614418, 2017). "Previous studies have demonstrated that IL-33 is an anti-inflammatory cytokine in many cardiovascular diseases and I/R injury, including myocardial I/R injury." (PMID 26571038, 2015). "A growing body of evidence has suggested that IL-33 plays a protective role in many cardiovascular diseases, including myocardial I/R injury, by suppressing inflammatory cytokine expression and inflammatory responses." (PMID 26571038, 2015).
cardiovascular diseases (continued). "Evidence indicates the interleukin 33/interleukin 1 receptor-like 1 (IL-33/ST2) axis participates in various fields of cardiovascular disease." (PMID 25517029, 2014). "According to the results of this study, while IL-33 levels are elevated in atopy and in some rheumatological diseases, its levels in cardiovascular disease are likely to be low possibly due to elevated sST2 levels." (PMID 24385685, 2013). "Today studies from animal models suggest that sST2 is more than just a marker in cardiovascular disease and implicate IL33/ST2 signaling as an important protective pathway in which the role of sST2 remains obscure." (PMID 22104207, 2011). "Future research is needed to gain a full understanding of the complex molecular mechanisms underlying the role of IL-33 in the diabetic and nondiabetic kidney and cardiovascular disease." (PMID 38899206, 2024). "Molecular mechanisms associated with the IL33/ST2 signaling pathways are discussed in view of the clinical usefulness of biomarkers to early diagnosis, evaluation therapy to response, and prediction of adverse outcomes in cardiovascular diseases." (PMID 35897800, 2022). "The IL-33/ST2 axis is involved in diverse areas of cardiovascular disease." (PMID 36337880, 2022). "With respect to IL-33, it remains to clarify whether it is mainly cardioprotective or contribute to endothelial inflammation, aggravating cardiovascular diseases." (PMID 34707513, 2021). "Hence, measurement of sST2 concentration can facilitate in better understanding of IL-33 contribution in cardiovascular disorders." (PMID 34754275, 2021). "Another GWAS linked SLC9A4 with regulation of IL-33/ST2 (suppression of tumorigenicity 2, part of the IL-1R family) signaling, which has previously been implicated in both immune and inflammatory diseases, including cardiovascular disease." (PMID 34134627, 2021). "Hence, IL-33 is involved in Th2 mediated inflammatory responses in AR, but has protective effects in cardiovascular disease." (PMID 32280308, 2020). "For example, IL-33 plays a protective role in cardiovascular diseases." (PMID 27699084, 2016). "It was also documented that suppression of tumorigenicity 2 (ST2) could bind interleukin-33 (IL-33) on inflammatory membranes, thereby restraining and facilitating development of cardiovascular disorders." (PMID 27821168, 2016). "For example, the protein expression of IL-33 and sST2 in endovascular epidermal cells and cardiomyocytes, respectively, is rapidly upregulated, and these proteins are secreted extracellularly, while cardiomyocytes or fibroblasts suffer mechanical damage due to cardiovascular disease." (PMID 36407452, 2022). "Therefore, sST2 levels are positively associated with cardiovascular disease severity, but this does not mean that IL-33 is always beneficial." (PMID 36684579, 2022). "However, there have been conflicting reports of the role of IL-33 in cardiovascular disease (CVD) and the potential of this axis in differentiating CVD patients and controls and with CVD disease severity, remains unclear." (PMID 34723980, 2021). "Thus, through its effects on monocytes and ECs, IL-33 could promote both inflammation and the formation of a prothrombotic state characteristic for patients with cardiovascular disease." (PMID 34948083, 2021). "Thus, IL-33 plays critical roles in cardiovascular diseases." (PMID 31235844, 2019). "Previous research showed that interleukin (IL)-33 can attenuate the level of inflammation and myocardial apoptosis after AMI, and has cardioprotective effects on various cardiovascular diseases." (PMID 39417451, 2024). "The IL-33/ST2 signaling pathway plays an essential role in inflammation, immune diseases, and cardiovascular diseases; therefore, sST2 cannot be used as an independent diagnostic factor of cardiovascular disease." (PMID 36407452, 2022). "Different disorders are related to the activity of IL-33, ST2, or their axis, including cardiovascular disease or renal disturbances." (PMID 30769901, 2019).
cardiovascular diseases (continued). "So far, therapies targeting the IL-33/ST2L/sST2 axis have not been tested in human cardiovascular diseases." (PMID 34707513, 2021). "Furthermore, the sST2 isoform acts as a decoy receptor to reduce IL-33 signaling through the ST2L receptor and is a significant predictor of mortality in patients with several cardiovascular disorders." (PMID 25517029, 2014). "For instance, the IL-33/ST2 signaling system may be particularly important in the heart response to stress and injury during cardiovascular diseases." (PMID 18836528, 2008). "In our own experience, IL-33 is not a strong direct predictor of outcome in cardiovascular disease." (PMID 34741120, 2021). "A precise role of IL-33 in the pathogenesis of cardiovascular diseases is still not well defined." (PMID 24725541, 2014). "So far, serum or plasma IL-33 has not been measured in cardiovascular disease." (PMID 24385685, 2013). "However, a possible role of IL-33 and ST2 in the pathogenesis of cardiovascular diseases is still not well defined." (PMID 23567618, 2013).
infectious disease (28 papers, 2011 to 2024). A disorder directly resulting from the presence and activity of a microbial, viral, or parasitic agent in humans. "IL-33 is a damage-associated molecular pattern factor, which can modulate host inflammatory responses in several infectious diseases." (PMID 26943125, 2016). "The IL-33/IL1RL1 axis plays diverse roles in various infectious diseases, and studies have suggested that it confers a protective effect against Group A Streptococcus infection by enhancing innate immunity." (PMID 38898675, 2024). "Our results confirm that, in response to cocktail cytokines, ILC2 upregulated CD86 and PD-L1, as observed in ILC2 from IL-33-treated mice and humans in infectious diseases, leading to an increase in the effector response." (PMID 38725998, 2024). "Interleukin-33 (IL-33) is a tissue-derived nuclear cytokine that plays a crucial immune modulator role in allergic, fibrotic, and infectious diseases." (PMID 33925682, 2021). "The role of the pro-inflammatory Th2 interleukin-33 (IL-33) has been investigated in various infectious diseases, where it was shown to have either a protecting effect against severe manifestations or a deleterious role favoring disease progression." (PMID 32571430, 2020). "A way to dissect the distinct roles of IL-33 on T cells is to study its effect in distinct infectious diseases." (PMID 30949175, 2019). "IL-33 has crucial and diverse roles in infectious diseases, depending on the type of infectious agents, acute or chronic infection stages, tissues involved, and host immune microenvironments." (PMID 26943125, 2016). "IL-33, a crucial amplifier of the innate immunity in infectious diseases as well as in autoimmune processes, is also a recently identified DAMP." (PMID 24507763, 2014). "Emerging evidence identified the immunomodulatory function of IL-33 in many infectious diseases." (PMID 36570798, 2022). "Because most of the current studies on the effect of IL-33 on poly-functional CD8+T cells were using mouse model, whether IL-33 can induce the polyfunctional CD8+T cells from humans in infectious diseases needs to be further investigated." (PMID 30564243, 2018). "However, emerging research indicates that IL-33 may also play a role in the immune response to infectious diseases, including TB." (PMID 38137331, 2023). "However, among them, IL-33 has been shown to be a Janus cytokine in infectious disease mechanisms." (PMID 36570798, 2022). "Therefore, IL-33 plays an important role in various infectious diseases." (PMID 36291105, 2022). "Interestingly, IL33 expression is not readily detectable in the large intestine, an organ containing high bacterial load and, similar to the stomach, susceptible to infectious disease." (PMID 28210674, 2015). "It has been reported that IL-33/ST2 pathway plays a key role in host defense and immune regulation in inflammatory and infectious diseases." (PMID 25032216, 2014). "FXBL19 targets the IL-33/IL1RL1 axis, crucial in infectious diseases and innate immunity promotion." (PMID 38898675, 2024). "We will highlight recent advances in our understanding of the IL-33 pathway and its impact on T cell differentiation and effector functions, including the modulatory role of IL-33 on Foxp3+ TREG cells, in both autoimmune and infectious diseases." (PMID 30949175, 2019). "Little is known about the role of IL-33 in human diseases, as there is currently a lack of tools to identify and follow human ST2+ T cells, yet important progress has been made in the field through rodent models of infectious disease." (PMID 30949175, 2019).